CCND1 (cyclin D1)
Diseases named in the same sentence as CCND1 in open-access papers (continued):
Sharing a sentence is not in itself a finding about the gene and the disease.
parathyroid adenomas (continued). "Cyclin D1 protein overexpression occurs in 20–40% of parathyroid adenomas, suggesting that increased PRAD1/cyclin D1 is one of the genetic abnormalities responsible for tumorigenesis in sporadic primary parathyroid adenomas, contributing to parathyroid hyperplasia in humans." (PMID 35208186, 2022). "Instead, promoter hypermethylation and down-regulation of various CDKIs could probably explain the commonly observed cyclin D1 upregulation in parathyroid adenomas." (PMID 33269427, 2021). "Although rare in sporadic parathyroid adenoma, overexpression of cyclin D1 is a common event, and therefore, other mechanisms apart from rare chromosomal inversions involving CCND1 or mutations in cyclin D1-regulating CDKIs are expected to play a role." (PMID 33269427, 2021). "Cyclin D1, a cell cycle regulator responsible for G1-S phase transition, is overexpressed in 20–40% of parathyroid adenomas, although a much higher proportion (~80%) of sporadic parathyroid adenomas from Asian Indians overexpress Cyclin D15." (PMID 28600574, 2017). "Cyclin D1, a G1-S phase regulator, is upregulated in parathyroid adenomas." (PMID 28600574, 2017). "Parathyroid adenomas are a common disease where cyclin D1 is overexpressed." (PMID 21176227, 2010). "Augmented cyclin D1 expression in some parathyroid adenomas could also be a consequence of aberrant β-catenin accumulation, although it remains to be determined whether CCND1 constitutes a β-catenin target in parathyroid cells." (PMID 18044981, 2007). "Interestingly, cyclin D1 over-expression is also found in a fraction of cases with secondary hyperparathyroidism, suggesting that a subset of these lesions are propelled in parts by processes similar to those present in parathyroid adenomas and carcinomas." (PMID 20208994, 2010). "CaSR, MEN1, CCND1/PRAD, CDKI, angiogenic factors like VEGF, FGF, TGFβ, and IGF1, and apoptotic factors are important genes in parathyroid adenomas pathogenesis that have been established by several studies." (PMID 37223014, 2023). "Gene expressions of cyclin D1 (CCND1) and regulatory molecules (CDKN2A, CDKN2B and RASSF1A) was analysed in parathyroid adenoma tissues (n = 30)." (PMID 28600574, 2017). "Sporadic nonfamilial parathyroid adenomas, associated with the cyclin D1/PRAD1 oncogene, are the classical indication for surgery, while hypercalcemia due to hyperplasia in all parathyroid glands as in the MEN1 syndrome (associated with MEN1 tumor suppressor gene) could be treated with cinacalcet." (PMID 21461394, 2011). "By PCR, macroarray, protein, and mRNA expression techniques, additional genes in parathyroid adenoma tissues were inserted in an involved gene list: APOLLON, BCL2, CK19, CK18, CHROMOGRANIN-A, BAX, PARATHORMONE, ATM,MDM2, CK8, CYCLIN D1, SYNAPTOPHYSIN, FLIP και TRAIL." (PMID 37223014, 2023). "In 1989, Arnold and colleagues found a genetic rearrangement in a parathyroid adenoma, this rearrangement, inv (p15; q13), positions the 5′ PTH gene regulatory region (located in 11p15) adjacent to the CCDN1 gene leading to the overexpression of cyclin D1 protein." (PMID 22567348, 2011).
Obesity (29 papers, 2013 to 2026). Accumulation of substantial excess body fat. "Obesity-associated inflammation is linked to the up-regulation of active β-Catenin, a pivotal component in the Wnt pathway, and several Wnt signaling target genes (Cyclin D1 and Axin 2)." (PMID 37185433, 2023). "The signal nucleotide polymorphism in CCND1 was linked with obesity; meanwhile, it might participate in the process of asthma initiation and development." (PMID 36105239, 2022). "SNP in CCND1 is linked with obesity, but this polymorphic gene may diagnose insulin resistance." (PMID 30678306, 2019). "In our study, DPR attenuates obesity‐induced cardiac remodeling during aging, as evidenced by the normalization of heart weight and the suppression of hypertrophic markers, including Cyclin D1, NPPA, and DDB1." (PMID 41549510, 2026). "From this analysis, methylation data (β values) of cancer-related genes previously identified in the DNA of leukocytes from patients with obesity after following a VLCKD to lose weight were isolated (CCND1, MAPK10, GLI2, LAMC3 and CTNNA2)." (PMID 40140215, 2025). "Luo and colleagues observed that hyperinsulinemia maintains the heightened hepatic expression of cyclin D1 in various models of obesity/diabetes." (PMID 39621069, 2024). "Significant increases were observed in Ccnd1, a cell cycle regulator that contributes to tumorigenesis, and Fasn, a fatty acid synthase that promotes obesity and tumorigenesis, in PFAS-exposed mice." (PMID 38251008, 2024). "The increases in Cyclin D1 at 100 ng/mL concentrations further emphasize leptin’s role in regulating cell cycle progression, promoting cellular proliferation, and fostering aggressive phenotypes characteristic of obesity-driven cases." (PMID 41562922, 2026). "Moreover, hsa-miR-15a-5p binds to CCND1, which is a molecule regulated by FTO, a gene identified as a risk gene for obesity." (PMID 37836393, 2023). "In addition, CCND1 increased significantly in diabetic patients’ liver and was one of the most significant genes in obesity/diabetes liver tumors." (PMID 35267929, 2022). "CCND1 has been shown to be involved in the pathogenesis of obesity, but this gene might be novel target for GDM." (PMID 33890634, 2021). "In our previous study, we found that BCM and the number of islets is increased in mice fed HSTD for 22 weeks, which show obesity and hyperglycemia and hyperinsulinemia, and that the expression levels of cyclin D1 and cyclin D2 mRNA in islets are increased in these mice." (PMID 31083314, 2019). "Similarly, genes ESR1, SERPINE1 and VEGFA are shared across diabetes (EGFR, GSTP1, SERPINE1, ESR1, VEGFA and EGF) and obesity (CCND1, SERPINE1, ESR1 and VEGFA), which is in line with previous reports that obesity is a risk factor of diabetes." (PMID 31835887, 2019). "Metformin increases m6A methylation levels of CCND1 and CDK2 by inhibiting FTO expression, thereby inhibiting adipogenesis and combating obesity." (PMID 36461116, 2022). "On the other hand, prostaglandin-endoperoxide synthase 2 (PTGS2), cyclin D1 (CCND1), and TFF1 (an ESR1 target gene) were elevated in rFNAs from postmenopausal women with obesity." (PMID 34485137, 2021). "Mature human adipocytes undergo senescence under obesity and hyperinsulinemia stimulation, exhibiting premature aging transcriptomic and secretory characteristics, including upregulation of CDKN2A, CDKN1A, and CCND1 gene expression, and downregulation of HMGB1 and HMGB2 gene expression." (PMID 39963130, 2025).
chronic lymphocytic leukemia (28 papers, 2010 to 2026). "Immunohistochemical staining showed CD20, CD5, and CD23 positivity, with Cyclin D1 negativity, confirming a diagnosis of small lymphocytic lymphoma (SLL) as a result of chronic lymphocytic leukemia (CLL)." (PMID 40897945, 2026). "A 60-year-old Saudi man known to have diabetes, hypertension, and chronic active hepatitis B was diagnosed as having Rai stage II chronic lymphocytic leukemia, with trisomy 12 and rearrangement of the CCND1 gene in December 2012." (PMID 29524963, 2018). "Cyclin D1 expression can be detected in a subset of cases of chronic lymphocytic leukemia (CLL) and/or small cell lymphoma (SLL) and hairy cell leukemia." (PMID 20350332, 2010). "Elevated expression of cyclin D1 has also been demonstrated in other lymphoproliferative disorders as hairy cell leukemia, plasma cell dyscrasias, rare cases of B-cell chronic lymphocytic leukemia/ small lymphocytic lymphoma and epithelial malignancies." (PMID 22770229, 2012). "miR-15a, along with miR-16, is commonly deleted in human chronic lymphocytic leukemia and known to target multiple oncogenes, including BCL2, MCL1, CCND1, and WNT3A." (PMID 23557329, 2013). "Atypical chronic lymphocytic leukemia (CLL) and small lymphocytic lymphoma (SLL) may also demonstrate positive for cyclin D1 but do not have CCND1 translocations and usually lack SOX-11 expression." (PMID 34442137, 2021). "Cyclin D2 is overexpressed in cyclin-D1-negative MCL, chronic lymphocytic leukemia/small lymphocytic lymphoma, and DLBCL." (PMID 30755239, 2019).
papillary thyroid carcinoma (28 papers, 2004 to 2026). "Cyclin D1 positivity was significantly associated both with FED cases with papillary carcinoma and with any kind of malignancy compared to FED only." (PMID 33991306, 2021). "Our findings suggest that induction of C-myc and Cyclin D1 gene transcription is a possible pathway for beta catenin, as an underlying source of papillary thyroid cancer’s aggressiveness." (PMID 32198408, 2020). "Additionally, a study discovered that the overexpression of CCND1 in papillary thyroid carcinoma (PTC) is linked to the aggressiveness and recurrence of the illness." (PMID 39188436, 2024). "Increased levels of Cyclin D1 are associated with inreased likehood of papillary carcinomas." (PMID 23327593, 2013). "The increase in Cyclin D1 suggests an association of Cyclin D1 staining with papillary carcinomas." (PMID 23327593, 2013). "FGF2 and CCND1 have been reported to play role in migration and invasion in papillary thyroid carcinoma." (PMID 35456223, 2022). "Other neoplasms such as papillary thyroid carcinomas have been found to express CD44ICD to sustain cell proliferation via CREB-dependent transcriptional activation of Cyclin D1." (PMID 33659040, 2021). "Perri et al31 demonstrated that triiodothyronine induced proliferation in papillary thyroid carcinoma cell lines via upregulation of cyclin D1 expression." (PMID 30707227, 2019). "In recent years, the elevated expression of Cyclin D1 in papillary carcinomas compared with papillomas has attracted significant attention." (PMID 23327593, 2013). "We therefore conclude that Cyclin D1 is expressed exclusively in the cancer stem or progenitor cells that positively co-immunostained for CK 8/18 in papillary carcinomas and predominantly for CK 8/18 the papilloma lesions." (PMID 23327593, 2013). "In our study, the rate of Cyclin D1 expression in papilloma cells was 0-37%, whereas the rate of Cyclin D1 expression in papillary carcinoma cells was 4.20%-60.80%." (PMID 23327593, 2013). "In this study, we evaluated the levels of Cyclin D1 expression in CK 5/6- or CK 8/18-positive cells from breast papilloma and papillary carcinoma." (PMID 23327593, 2013). "We detected negligible levels of Cyclin D1 expression within papilloma sections compared with high levels of Cyclin D1 expression in papillary carcinomas." (PMID 23327593, 2013). "Although Cyclin D1 is an effective marker for the differential diagnosis of other papillary lesions, it cannot be used to distinguish between papilloma and papillary carcinoma lesions because its expression occurs in both lesions." (PMID 23327593, 2013). "In papillary carcinomas, Cyclin D1 exhibited a mean 34.74% (34.74% ± 16.32%) co-expression rate with Cytokeratin 8/18 compared with a co-expression rate of 0.70% (0.70% ± 0.93%) with Cytokeratin 5/6 (p < 0.01)." (PMID 23327593, 2013). "In our results, Cyclin D1 staining was predominantly detected in the cells that were also immunoreactive for CK 8/18 in either the papillary carcinomas or papillomas." (PMID 23327593, 2013). "Cyclin D1 is highly expressed in papillary carcinomas (27.54% ± 15.43%) compared with papillomas (8.81% ± 8.41%, p < 0.01)." (PMID 23327593, 2013). "This study also demonstrated the usefullness of CK 5/6 in distinguishing breast papilloma (Cyclin D1 < 4.20%) from papillary carcinoma (Cyclin D1 > 37.00%)." (PMID 23327593, 2013). "In this study, we aimed to evaluate the expression of Cyclin D1 in different cell types and to assess its potential to distinguish between papillomas and papillary carcinomas using a double immunostaining technique." (PMID 23327593, 2013). "Some human thyroid nodular goitre and differentiated thyroid carcinoma presenting morphology and nuclear features similar to E7 mouse model also showed stromal cell-positive staining for Cyclin D1." (PMID 18985036, 2008). "Cyclin D1 is highly expressed in papillary thyroid carcinoma (PTC)." (PMID 37427143, 2023).
papillary thyroid carcinoma (continued). "Additionally, in papillary thyroid cancer model, silencing of ETV5 causes a decrease in cell proliferation and this was associated with a diminished expression of CCND1 (cyclin D1) and CCND2 (cyclin D2)." (PMID 37876309, 2023). "The positive predictive value (PPV) and median stain ratio (MSR) of cyclin D1 nuclear staining was determined in papillary thyroid carcinoma (PPV = 91.5%, MSR = 48.5%), follicular adenoma (PPV = 66.7%, MSR = 13.1%), and adenomatous goiter and inflammation controls (MSR = 3.4%)." (PMID 30885146, 2019). "The distinct expression patterns of Cyclin D1 between the papillomas and papillary carcinomas might be explained by their occurrence during different stages of tumorigenesis." (PMID 23327593, 2013). "In keeping with these results, the mean rate of Cyclin D1 expression in the papillomas was 8.81% (8.81% ± 8.41%), whereas the mean expression rate of Cyclin D1 in the papillary carcinomas exhibited a statistically significant increase to 27.54% (27.54% ± 15.43%, p < 0.01)." (PMID 23327593, 2013). "Statistical analysis indicated that Cyclin D1 expression could distinguish papilloma from papillary carcinoma (p < 0.01)." (PMID 23327593, 2013). "Moreover, the use of Cyclin D1 alone to make a differential diagnosis between papilloma and papillary carcinoma remains a controversial topic." (PMID 23327593, 2013). "In addition, our data suggest that Cyclin D1 is expressed only in the cancer stem or progenitor cells that co-immunostained with CK 8/18 in papillary carcinomas, and predominantly with CK 8/18 in the papillomas." (PMID 23327593, 2013). "The hypothesis that papillary carcinoma cells could be derived from papilloma cells which have the same progenitors as the cancer cells might be explained by the expression pattern of Cyclin D1 in cells co-expressing CK 8/18." (PMID 23327593, 2013). "In addition, studies have found that Cyclin D1 is a molecular marker for the dedifferentiation of papillary thyroid carcinoma into anaplastic papillary carcinoma, indicating an imbalance in cell cycle control and increased proliferative activity in anaplastic papillary carcinoma." (PMID 37951919, 2023). "Targeting CCND1 and its OS-mediated regulatory pathways offers a promising therapeutic strategy for PTC.CCND1, oxidative stress, papillary thyroid carcinoma, single-cell RNA sequencing, SOX4, TFF3." (PMID 41646983, 2026). "In papillary thyroid carcinoma (PTC) and follicular thyroid carcinoma (FTC)-derived cell lines, metformin inhibited cancer cell growth and down-regulated cyclin D1 expression." (PMID 37773165, 2023). "In the primary papillary carcinoma cells (“C1/C2”), treatment with ARV-825 (100 nM, 24h) similarly induced BRD4 protein degradation as well as downregulation of c-Myc, Bcl-xL and cyclin D1." (PMID 32163373, 2020). "Of note, among the downregulated genes MMP2, VEGFA, CCND1, and TWIST1 were downregulated only in papillary carcinoma but were either unchanged or upregulated in other two subtypes." (PMID 30863721, 2019). "Based on these findings, we posit that differentiated thyroid carcinoma has slow cell proliferation; however, several ATC showed random staining patterns and low levels of cyclin D1." (PMID 30885146, 2019). "Statistically, cyclin D1 positivity was significantly higher in FED cases with papillary carcinoma than in FED without neoplasia (p = 0.018), also in all malignant tumors in comparison to FED without neoplasia (p = 0.008)." (PMID 33991306, 2021). "Other studies showed that most papillary carcinomas express CD44 and cyclin D1, whereas it is less common in follicular neoplasm and nodular goiter, suggesting that could be helpful in diagnostically difficult cases." (PMID 31341476, 2019). "Cyclin D1 was almost exclusively expressed in the cells that co-expressed CK 8/18, whereas CK 5/6 is almost never expressed in the papillary carcinomas." (PMID 23327593, 2013).
papillary thyroid carcinoma (continued). "Our results show that Cyclin D1 and CK 5/6 staining could be used in concert to distinguish between the diagnosis of papilloma (Cyclin D1 < 4.20%, CK 5/6 positive) or papillary carcinoma (Cyclin D1 > 37.00%, CK 5/6 negative)." (PMID 23327593, 2013). "As expected, almost all the thyroid papillary carcinomas tested as controls showed coexpression of galectin-3, HBME-1, c-met protein and cyclin D1 (data not shown)." (PMID 15292926, 2004).
follicular lymphoma (27 papers, 2007 to 2025). Follicular lymphoma is a form of non-Hodgkin lymphoma characterized by a proliferation of B cells whose nodular structure of follicular architecture is preserved. "In our case, although we considered the possibility of metastatic BC when analyzing the mesenteric biopsy, the immunohistochemical profile clearly revealed a nodular, low-grade (grade I) follicular lymphoma (CD20+, CD10+, BCL2+, CD23+, CD3−, CD5− and cyclin D1−)." (PMID 23419985, 2013). "Notably, the B cells in the atypical nodules were negative for BCL2 and cyclin D1, crucial in distinguishing PTFL from adult-type follicular lymphoma." (PMID 39840177, 2024).